HACD1 (3-hydroxyacyl-CoA dehydratase 1)
Description:
[Isoform 1]: Catalyzes the third of the four reactions of the long-chain fatty acids elongation cycle. This endoplasmic reticulum-bound enzymatic process, allows the addition of two carbons to the chain of long- and very long-chain fatty acids/VLCFAs per cycle. This enzyme catalyzes the dehydration of the 3-hydroxyacyl-CoA intermediate into trans-2,3-enoyl-CoA, within each cycle of fatty acid elongation. Thereby, it participates in the production of VLCFAs of different chain lengths that are involved in multiple biological processes as precursors of membrane lipids and lipid mediators. [Isoform 2]: In tooth development, may play a role in the recruitment and the differentiation of cells that contribute to cementum formation. May also bind hydroxyapatite and regulate its crystal nucleation to form cementum.
Synonyms: CAP; PTPLA; CMYO11; CMYP11; MYONP
Tractability: Antibody: UniProt predicts a signal peptide or a membrane-spanning region. PROTAC: ubiquitination databases record sites on it.
Gene: Protein-coding gene on chromosome 10 (17,588,316 to 17,617,430, reverse strand). Ensembl gene ENSG00000165996.
Subcellular location: Endoplasmic reticulum membrane (Isoform 1)
Pathways (Reactome):
Metabolism: Synthesis of very long-chain fatty acyl-CoAs
Gene Ontology:
Molecular function: 3-hydroxyacyl-CoA dehydratase activity; protein binding; very-long-chain (3R)-3-hydroxyacyl-CoA dehydratase activity; (2E)-enoyl-CoA hydratase activity
Biological process: fatty acid elongation; long-chain fatty-acyl-CoA biosynthetic process; sphingolipid biosynthetic process; fatty acid biosynthetic process
Cellular component: endoplasmic reticulum membrane
Genetic constraint (gnomAD): Loss-of-function variants: 34 observed, 23.64 expected, observed/expected ratio (o/e) 1.44, 90% interval 1.09 to 1.85. The synonymous counts are far from expectation, so gnomAD's model fits this gene poorly and the ratio says little. Missense variants: 359 observed, 292.25 expected, observed/expected ratio (o/e) 1.23, 90% interval 1.13 to 1.34. Synonymous variants: 135 observed, 106.55 expected, observed/expected ratio (o/e) 1.27, 90% interval 1.1 to 1.46.
Gene-disease validity (ClinGen):
ClinGen rates the evidence that HACD1 causes each of these diseases.
congenital myopathy (autosomal recessive): Definitive.
Homologues: Orthologues: chimpanzee HACD1 (98% identical), macaque HACD1 (96% identical), dog HACD1 (92% identical), pig HACD1 (91% identical), guinea pig HACD1 (82% identical), rat Hacd1 (81% identical), mouse Hacd1 (80% identical), rabbit HACD1 (69% identical), zebrafish hacd1 (63% identical), tropical clawed frog hacd1 (62% identical), Caenorhabditis elegans hpo-8 (31% identical), Drosophila melanogaster Hacd1 (26% identical). Paralogues in human: HACD2 (52% identical), HACD3 (22% identical), HACD4 (18% identical).
Diseases named in the same sentence as HACD1 in open-access papers:
HACD1 is named in the same sentence as 17 diseases in open-access papers, as found by Europe PMC text mining. Sharing a sentence is not in itself a finding about the gene and the disease. The quoted sentences say what the papers report.
congenital myopathy (7 papers, 2013 to 2025). "Of note, mutations in HACD1 gene encoding an enzyme involved in the modulation of very-long-chain fatty acids, have been associated with a congenital myopathy." (PMID 36830771, 2023). "HACD1 contributes to muscle growth through regulation of myocyte fusion and HACD1 loss-of-function mutations are associated with a congenital myopathy." (PMID 34740639, 2022). "For example, pathogenic variants of HACD1 (3-hydroxyacyl-CoA dehydratase 1), an ER resident enzyme involved in the synthesis of very long-chain fatty acids, have been associated with congenital myopathies in humans and in dogs." (PMID 34360941, 2021). "In humans and dogs, HACD1 deficiency leads to a congenital myopathy with fibre size disproportion associated with a generalized muscle weakness." (PMID 26160855, 2015). "We suggest that the mutation in the HACD1 gene causes a reduction in the synthesis of VLCFAs, which are components of membrane lipids and participants in physiological processes, leading to congenital myopathy." (PMID 23933735, 2013). "In summary, we demonstrate that impaired HACD1 enzyme activity, involved in third step elongation of VLCFA, causes congenital myopathy that improves with age." (PMID 23933735, 2013). "Similarly, 3-hydroxyacyl-CoA dehydratase 1 (HACD1) deficiency in humans and dogs leads to congenital myopathy with fibre size disproportion associated with generalized muscle weakness." (PMID 38032316, 2024). "In conclusion, we propose that fusion impairment constitutes a novel, non-exclusive pathological mechanism operating in congenital myopathies and reveal that HACD1 is a key regulator of a lipid-dependent muscle fibre growth mechanism." (PMID 26160855, 2015).
breast carcinoma (1 paper, 2022). "Meanwhile, several other risk model genes were identified in this study (ST6GALNAC4, PLPP2, ELOVL1, HACD1, VAPB, CERS2, ALDH3B2, and HACD3) have not yet been explored in depth in breast cancer." (PMID 36059802, 2022).
congenital cardiomyopathy (1 paper, 2025). "Under normal conditions, FGF21 loss had minimal effects on most cardiac FAO genes, except peroxisomal Ehhadh, Hsd17b4, and ER-residing Hacd1/2 (linked to congenital cardiomyopathy)." (PMID 40998786, 2025).
tumor (3 papers, 2022 to 2023). "We detected seven pairs of ccRCC tissues and corresponding para-carcinoma tissues and found a significantly lower level of ACADM and ACAT1 mRNA and a higher level of CPT1B and HACD1 mRNA in tumor tissues." (PMID 35873479, 2022). "Compared with normal tissues, three genes (CYP17A1, HACD1, and MTMR10) were down-regulated in tumor tissues, while the others were up-regulated." (PMID 35295857, 2022).
infection (1 paper, 2010). The state of being infected such as from the introduction of a foreign agent such as serum, vaccine, antigenic substance or organism. "Furthermore, the fasting-induced gene hacd-1 was repressed during infection." (PMID 20617181, 2010).
HACD1 also shares sentences with these, for which no sentence is quoted: centronuclear myopathy (7 papers); cancer (2); Obesity (2); clear cell renal cell carcinoma (1); genetic diseases (1); Glucose intolerance (1); heart disease (1); neuroblastoma (1); prostate carcinoma (1); retinal degeneration (1); type 2 diabetes (1); uveal melanoma (1).